RASA1 (RAS p21 protein activator 1)
Diseases named in the same sentence as RASA1 in open-access papers (continued):
Sharing a sentence is not in itself a finding about the gene and the disease.
melanoma (continued). "This study is the first demonstration of the role of RASA1 in the development of melanoma." (PMID 26993606, 2016). "In summary, RASA1 plays tumor suppressive roles in melanomas with BRAF activation." (PMID 26993606, 2016). "Although not frequently mutated, it is possible that R-Ras activation via inactivation of RASA1 may play important roles in melanoma." (PMID 26993606, 2016). "Interestingly, RASA1 alterations in melanoma are significantly more clustered in or around the PH domain than expected by chance (Randomization test, p-value < 0.001) and target highly conserved amino acids among different species." (PMID 26993606, 2016). "Therefore, RASA1 expression was frequently down-regulated in metastatic melanoma samples compared to primary melanomas and atypical nevi." (PMID 26993606, 2016). "Possible cooperative interactions between activation of BRAF/MEK/ERK and RASA1/R-Ras/Ral-A pathways may explain the observed decreased overall survival of melanoma patients, who have low levels of RASA1 expression and BRAF mutations." (PMID 26993606, 2016). "RasGAPs can inactivate wild type but not mutant Ras proteins and low level of RASA1 mRNA expression is associated with decreased overall survival of melanoma patients with a BRAF mutation; therefore, we addressed RASA1 function in melanoma cell lines containing BRAF mutations." (PMID 26993606, 2016). "Therefore, RASA1 consistently suppresses Ral-A activation in these BRAF activated melanoma cell lines." (PMID 26993606, 2016). "Thus, loss of RASA1 expression promotes anchorage-independent colony formation and tumor growth, supporting that RASA1 plays a tumor suppressive role in melanoma." (PMID 26993606, 2016). "In melanoma cells harboring activating NRAS mutation, RASA1 may play differential roles as a signaling adaptor/scaffold protein, since RASA1 cannot function as a RasGAP on mutated Ras isoforms." (PMID 26993606, 2016). "Thus, genetic alterations of RASA1 occur in melanoma, although the frequency is low." (PMID 26993606, 2016). "Having shown that RASA1 regulates R-Ras activity and that R-Ras regulates Ral-A activity in BRAF mutant melanoma, we next addressed if Ral-A activity was stimulated or suppressed by RASA1 knockdown or overexpression, respectively." (PMID 26993606, 2016). "Since RASA1 mutation rate was low in melanoma, we determined the expression level of RASA1 in melanocytic lesions in vivo by immunohistochemical analysis on a melanoma TMA containing atypical (Clark's) nevi, primary melanomas, lymph node metastases, and distant metastases." (PMID 26993606, 2016). "RASA1 functions as a RasGAP for the R-Ras isoform, for which a role has not been appreciated previously in melanoma tumorigenesis." (PMID 26993606, 2016). "Asides from these physiological roles of RASA1, its importance in tumorigenesis, particularly in melanoma, has not been addressed previously." (PMID 26993606, 2016). "In addition, we addressed the expression pattern of RASA1 in a melanoma TMA containing dysplastic nevi, primary, and lymph node and distant metastatic melanomas and observed frequent RASA1 down-regulation in metastatic melanomas." (PMID 26993606, 2016). "We have shown that wild type RASA1, but not identified mutants, suppresses soft agar colony formation and tumor growth of BRAF mutated melanoma cell lines via its RasGAP activity toward R-Ras (related RAS viral (r-ras) oncogene homolog) isoform." (PMID 26993606, 2016). "While NF1 shows higher activity toward K- and H-, but not N-Ras in melanoma, RASA1 has increased activity toward R-Ras compared with H-Ras." (PMID 26993606, 2016).
myocardial infarction (3 papers, 2019 to 2022). Gross necrosis of the myocardium, as a result of interruption of the blood supply to the area, as in coronary thrombosis. "Hsa-miR-223 and hsa-miR-144-3P regulate fibrosis after myocardial infarction by targeting RAS p21 protein activator 1 (RASA1) and phosphatase and tensin homolog (PTEN), respectively." (PMID 35235759, 2022). "RAS p21 protein activator 1 (RASA1) is involved in miR-223 mediated cardiac fibrosis after myocardial infarction." (PMID 33889087, 2021). "MicroRNA 223-3p also regulated cardiac fibrosis after myocardial infarction by targeting RASA1, and regulated expression of voltage-gated K+ channel Kv4.2 in acute myocardial infarction." (PMID 31672150, 2019). "microRNA 223-3p is another widely documented microRNA which has been reported to regulate cardiac fibrosis after myocardial infarction by targeting RAS p21 protein activator 1 (RASA1), and regulated expression of voltage-gated K+ channel Kv4.2 in acute myocardial infarction." (PMID 31672150, 2019).
pancreatic cancer (3 papers, 2012 to 2021). "RASA1 has a tumor suppressor effect in colorectal and pancreatic cancers, but its role in VSMCs is still unknown." (PMID 34238206, 2021).
Venous malformation (3 papers, 2021 to 2025). A vascular malformation resulting from a developmental error of venous tissue composed of dysmorphic channels lined by flattened endothelium and exhibiting slow turnover. "PKWS is defined by mAVFs, often presenting with secondary venous malformations and CMs, usually accompanied by increased skin temperature and RASA1 mutations." (PMID 40483475, 2025).
capillary malformation-arteriovenous malformation syndrome (2 papers, 2015 to 2025). This syndrome is characterized by the association of multiple capillary malformations (CM) with an arteriovenous malformation (AVM) and arteriovenous fistulas. "Our systematic review highlights distinct cerebrovascular phenotypes associated with RASA1 versus EPHB4 mutations in CM-AVM syndrome." (PMID 41398316, 2025). "Capillary malformation-arteriovenous malformation syndrome (CM-AVM; OMIM 608354) is a familial syndrome caused by mutations in RASA1." (PMID 26192947, 2015). "However, not all 300 were diagnosed with CM-AVM syndrome; most had RASA1 mutation polymorphisms, with only a subset confirmed to have the syndrome." (PMID 41398316, 2025).
cardiac hypertrophy (2 papers, 2022 to 2025). "Inhibits angiogenic function of CMECs by decreasing the PI3K/Akt signal activity, regulates cardiac hypertrophy by modulating the p-Akt activation, and mediates cardiac fibrosis after MI targeting RASA1 expression, which promotes MEK1/2, ERK1/2 and AKT phosphorylation." (PMID 35563860, 2022).
intracranial AVM (2 papers, 2016 to 2025). "Despite these overlapping features, RASA1 mutations may still be more frequently associated with intracranial AVMs than EPHB4 mutations, although this remains statistically unproven." (PMID 41398316, 2025).
lung adenocarcinoma (2 papers, 2013 to 2019). A carcinoma that arises from the lung and is characterized by the presence of malignant glandular epithelial cells. "Recent sequencing data shows that RASA1 mutations are observed in lung adenocarcinoma (COSMIC database), so further effort should be directed towards understanding the relationship between RASA1, DOK2, EGFR, and KRAS in lung adenocarcinoma." (PMID 24255704, 2013).
metastatic tumors (2 papers, 2021 to 2023). "Therefore, we speculate that these differentiated cancer cells in metastatic tumors exhibit low YAP and Wnt activity and may be less reliant on YAP and Wnt signaling regulated by the loss of NF2 and RASA1, compared to CSCs." (PMID 37730636, 2023).
osteosarcoma (2 papers, 2015 to 2025). A usually aggressive malignant bone-forming mesenchymal neoplasm, predominantly affecting adolescents and young adults. "Finally, we investigated how the increased prevalence of GTP-bound KRAS enhanced the sensitivity of KRAS wild-type osteosarcoma cells to daraxonrasib using siRNA targeting RASA1." (PMID 40779492, 2025). "We further demonstrated that daraxonrasib inhibition of osteosarcoma depended on the ratio of the active form of KRAS, as demonstrated by the increased daraxonrasib sensitivity of HOS cells that was induced by knockdown of RASA1." (PMID 40779492, 2025).
sarcoma (2 papers, 2023 to 2024). A usually aggressive malignant neoplasm of the soft tissue or bone. "Interestingly, cytoskeleton proteins, including RASA1, RASAL2, NCKAP5, MACF1 and ARHGAP24, were reduced following differentiation, indicating that the sarcoma microenvironment induces resident‐like myeloid cell transfer." (PMID 39658531, 2024).
Telangiectasia (2 papers, 2025 to 2026). Telangiectasias refer to small dilated blood vessels located near the surface of the skin or mucous membranes, measuring between 0.5 and 1 millimeter in diameter. "Hereditary Haemorrhagic Telangiectasia (HHT), Activin A Receptor Like Type 1 (ACVRL1), Mothers Against Decapentaplegic homolog 4 (SMAD4), Phosphatase and Tensin homolog (PTEN), Ras p21 protein activator 1 (RASA1), PIK3 CA and Ephrin 4 (EPHB4) testing were all negative for pathogenic mutation." (PMID 40490531, 2025).
Alagille syndrome (1 paper, 2019). "Whole exome sequencing (WES) identified a paternally inherited RASA1 heterozygous pathogenic variant p.(Ser219Ter) causing CM-AVM and a de novo NOTCH2 heterozygous variant p.(Met2042Thr) associated with Alagille syndrome." (PMID 31749841, 2019).
brainstem glioma (1 paper, 2024). "The RASA1 c.2656 C > T (p.(Pro886Ser) variant was found in N75, a ten years’ old patient, with an early diagnosis (at 8 months of age), based on the presence of CALs and lentigo, who, at 4 years of age, developed a brainstem glioma that remained radiologically stable and clinically asymptomatic." (PMID 38874808, 2024).
capillary hemangioma (1 paper, 2020). A common hemangioma characterized by the presence of capillary-sized vascular channels without prominent epithelioid endothelial cells. "RASA-1– and HHT-related mutations (ENG and ACVRL1) were most commonly associated with clinical phenotypes including cranial lesions, hypercoagulable state, spinal AVF/AVM, capillary hemangioma (in RASA-1)." (PMID 33041990, 2020).
cerebrovascular disorder (1 paper, 2026). A disorder resulting from inadequate blood flow in the vessels that supply the brain. "The RASA1 gene is mutated in cerebrovascular disorders and cancer, yet how the resulting mutations in the GTPase Activating Protein, RasGAP (p120RasGAP, RASA1) dysregulate signaling remains poorly understood." (PMID 42208894, 2026).
cervical cancer (1 paper, 2020). A primary or metastatic malignant neoplasm involving the cervix. "Similarly, the miR-21/RASA1 axis was described in cervical cancer and esophageal squamous cell carcinoma, where miR-21 enhances Ras signaling and EMT." (PMID 33096593, 2020). "High levels of miR-21 were found in the serum of cervical cancer patients, suggesting that secreted miR-21 can mediate RASA1 inhibition in a cell non-autonomous manner." (PMID 33096593, 2020).
colitis (1 paper, 2024). Inflammation of the colon. "Based on these findings, we have demonstrated that CrF‐EVs have significant beneficial roles in improving lymphatic functions and alleviating colitis and mesenteritis via the miR‐132‐3p/RASA1/ERK1/2 axis." (PMID 39623906, 2024). "Mechanistically, CrF‐EVs mitigate colitis and mesenteritis by delivering miR‐132‐3p to LECs and targeting the RASA1/ERK1/2 axis, which promotes lymphangiogenesis and improves lymphatic drainage function." (PMID 39623906, 2024). "Extracellular vesicles (EVs) derived from adipose tissue‐derived stem cells in creeping fat (CrF) improve lymphatic functions and increase mesenteric lymphatic vessel density of Il‐10‐/– mice, leading to decreased colitis and mesenteritis through the miR‐132‐3p/RASA1 /ERK1/2 axis." (PMID 39623906, 2024). "Therefore, CrF‐EV injection regulated colitis and mesenteritis of Il‐10−/− mice through miR‐132‐3p/RASA1/ERK1/2‐dependent improvement of lymphatic endothelial functions." (PMID 39623906, 2024). "In this study, CrF‐EV‐miR‐132‐3p promoted lymphangiogenesis and lymphatic drainage function via the RASA1/ERK1/2 axis, which effectively attenuated colitis and mesenteritis in CD." (PMID 39623906, 2024).
congenital capillary malformations (1 paper, 2024). "Recent studies revealed that mutations in the RASA-1 gene on 5q13-22 are responsible for many congenital capillary malformations and AVMs." (PMID 38882955, 2024).
Facial hemangioma (1 paper, 2024). Hemangioma, a benign tumor of the vascular endothelial cells, occurring in the face. "Therefore, it is possible to hypothesize that the RASA1 variant in our patient may be responsible for the facial hemangiomas." (PMID 38874808, 2024).
heart failure (1 paper, 2022). Inability of the heart to pump blood at an adequate rate to meet tissue metabolic requirements. "A RAF1-deficient male and a RASA1-deficient male survived from severe heart failure by surgical interventions in early life." (PMID 36002837, 2022).
lymph node metastases (1 paper, 2016). "Positive RASA1 staining was observed in 44.1% (15/34) of Clark's nevi, 33.3% (21/63) of primaries, 11.4% (4/35) of lymph node metastases, and 3.4% (1/29) of distant metastases." (PMID 26993606, 2016).
oral carcinoma (1 paper, 2019). "Three out of the 15 BQ‐TC cases harbored RASA1 mutations, while there were only four RASA1 mutations in the 82 TCGA cases and nine in the 201 TCGA‐ORCA cases (oral carcinoma from TCGA project)." (PMID 30672146, 2019).
renal fibrosis (1 paper, 2025). A final common manifestation of a wide variety of chronic kidney diseases characterized by glomerulosclerosis and tubulointerstitial fibrosis. "Among these mechanisms, hypermethylation of the RASA1 gene stands out, associated with renal fibrosis and deterioration of renal function." (PMID 41226547, 2025).
Sepsis (1 paper, 2021). Sepsis is defined as life-threatening organ dysfunction caused by a dysregulated host response to infection. "MiR-223 was found to alleviate sepsis by binding to the mRNA of NFAT5 and Rasa1 and causing IL-4-meditated M2 macrophage differentiation." (PMID 34956210, 2021). "Indeed, miR-223 was a critical factor in regulating IL-4-induced M2 differentiation of macrophages by controlling Nfat5 and Rasa1 protein production, thus modulating the pathophysiology of sepsis." (PMID 34956210, 2021).
squamous cell carcinoma (1 paper, 2019). A carcinoma arising from squamous epithelial cells. "Interestingly, in this study, RASA1-encoding p120RasGAP, a partner of p190A, was also found mutated in squamous cell carcinomas, suggesting that p190A/p120RasGAP pathway may be involved in lung carcinogenesis." (PMID 31013840, 2019).
T-cell acute lymphoblastic leukemia (1 paper, 2024). Acute lymphoblastic leukemia of T-cell origin. "In addition, the co-deletion of RASA1 and NF1 results in the development of T-cell acute lymphoblastic leukemia." (PMID 38874808, 2024).
tongue cancer (1 paper, 2019). A malignant neoplasm affecting the tongue. "By whole‐genome and whole‐exome sequencing, we studied the genetic features of BQ‐TC and found that BQ chewing defined a distinct group of tongue cancer with characteristic mutational signature and frequent mutations in RASA1 gene and CpG islands." (PMID 30672146, 2019). "Altogether we identified seven samples harboring RASA1 nonsynonymous mutations in the 102 tongue carcinomas that we analyzed (15 BQ‐TC, 5 nBQ‐TC, and 82 TCGA‐TC)." (PMID 30672146, 2019). "(b) The BQ‐TC had a distinct mutational signature from that of nBQ‐TC and tongue carcinomas in the general population, and this signature was associated with the mutations in RASA1 and in CpG islands." (PMID 30672146, 2019). "The GCG (to GTG) pattern is the dominant pattern in these seven RASA1 mutant cases, while in the rest of the 95 tongue carcinoma samples, TCG (to TTG) is the dominant pattern." (PMID 30672146, 2019).
tumor (65 papers, 2005 to 2025). "M62I mutation of DUSP6 was identified in all three osimertinib-resistant PDX tumors, while T846A, N850S, or I931T mutation of RASA1 was detected in at least one osimertinib-resistant PDX tumor." (PMID 39528952, 2024). "Rasa1 is a regulator of Ras GDP/GTP, and mutations or aberrant expression of RASA1 contribute to pathological processes in tumor formation, chiefly via aberrant activation of Ras/RAF/MEK/ERK or Ras/PI3K/AKT signaling." (PMID 37730636, 2023). "Using TMA analyses of human GC tissues, we found that histologically high-grade GC had significantly lower RASA1 expression levels than did low-grade tumor cells, suggesting that RASA1 loss is associated with loss of tumor differentiation." (PMID 37730636, 2023). "Although previous clinical evidence has linked Rasa1 loss to cancer metastasis, most functional studies have focused on primary tumor growth and progression through the enhancement of RAS-ERK signal amplification." (PMID 37730636, 2023). "Pathological angiogenesis in response to tumor growth is another form of neoangiogenesis that is inhibited following induced loss of RASA1 in adult mice." (PMID 35015735, 2022). "In kidney tumorigenesis, loss of QKI-5 destabilizes RASA1 mRNA and favors Ras signaling-mediated cancer cell survival and tumor growth." (PMID 33096593, 2020). "Another interesting candidate tumor suppressor gene in aggressive cSCC is RAS p21 protein activator 1 (RASA1), found mutated in 13% of analyzed cases, with 66% of its mutations predicted to truncate or eliminate the protein." (PMID 32674318, 2020). "Similarly, the Del1|0 and Ins1A mutations of Rasa1 started with the frequencies at around 50% in parental 1C3-1 clone and then oscillated in a reverse pattern among single-cell clones from tumor grafts." (PMID 37803452, 2023). "Despite the fact that RASA1 is frequently inactivated by mutation in many other tumor types, its role in cSCC and cancer in general remains unclear." (PMID 32674318, 2020). "Inactivating mutations and deletions in the RASA1 gene have also been detected in a number of cancers, such as lung squamous carcinoma, stomach, esophagus, leukemia, and head and neck cancer, but its role as a tumor suppressor is less well defined." (PMID 30858928, 2019). "Functional domain analysis of APC-COMMD10 and RASA1-LOC644100 fusion genes showed truncation of APC (293 aa/325 aa) and RASA1 (179 aa/253 aa), respectively, which may induce loss of function of each tumour suppressor." (PMID 29955133, 2018). "Additionally, the identified mutations in RASA1 have functional impacts in that the Y472H mutation promoted tumor growth and the L481F mutation down-modulated a tumor suppressive role." (PMID 26993606, 2016). "The analysis of the transposon integration sites identified several candidate genes, of which Man1a1, Pkp4, Rab10, Rasa1, Trps1, Vps26a, Xpnpep3 and Znf326 accelerated tumor growth, whereas the silencing of R3hcc1l reduced tumor growth." (PMID 36497409, 2022). "This patient had six verified tumor mutations (ARID1B, ATM, CDK8, FANCA, and two RASA1 mutations), all of which were detected in the preoperative plasma sample." (PMID 30554450, 2019). "Genetic analysis of tumor samples only identified a significant number of inactivating mutations in the RASGAPs neurofibromin (NF1) and RASA1 (p120GAP), suggesting that these two RASGAPs can function as tumor suppressors." (PMID 30858928, 2019). "Recently, pituitary homeobox 1 (PITX1) was reported to act as a tumor suppressor in hepatocarcinogenesis by activating the expression of p120RasGAP (also known as Ras p21 protein activator 1 (RASA1)), triggering Ras inactivation by converting GTP into GDP." (PMID 29558404, 2018).